SMARCD3 (SWI/SNF related BAF chromatin remodeling complex subunit D3)
Description:
Involved in transcriptional activation and repression of select genes by chromatin remodeling (alteration of DNA-nucleosome topology). Component of SWI/SNF chromatin remodeling complexes that carry out key enzymatic activities, changing chromatin structure by altering DNA-histone contacts within a nucleosome in an ATP-dependent manner. Stimulates nuclear receptor mediated transcription. Belongs to the neural progenitors-specific chromatin remodeling complex (npBAF complex) and the neuron-specific chromatin remodeling complex (nBAF complex). During neural development a switch from a stem/progenitor to a postmitotic chromatin remodeling mechanism occurs as neurons exit the cell cycle and become committed to their adult state. The transition from proliferating neural stem/progenitor cells to postmitotic neurons requires a switch in subunit composition of the npBAF and nBAF complexes. As neural progenitors exit mitosis and differentiate into neurons, npBAF complexes which contain ACTL6A/BAF53A and PHF10/BAF45A, are exchanged for homologous alternative ACTL6B/BAF53B and DPF1/BAF45B or DPF3/BAF45C subunits in neuron-specific complexes (nBAF). The npBAF complex is essential for the self-renewal/proliferative capacity of the multipotent neural stem cells. The nBAF complex along with CREST plays a role regulating the activity of genes essential for dendrite growth (By similarity).
Synonyms: BAF60C; Rsc6p; CRACD3
Tractability: PROTAC: ubiquitination databases record sites on it; its protein half-life has been measured.
Gene: Protein-coding gene on chromosome 7 (151,238,764 to 151,277,896, reverse strand). Ensembl gene ENSG00000082014.
Subcellular location: Nucleus
Subcellular location (Human Protein Atlas): Nucleoplasm
Pathways (Reactome):
Chromatin organization: Formation of neuronal progenitor and neuronal BAF (npBAF and nBAF); Formation of the embryonic stem cell BAF (esBAF) complex; Formation of the non-canonical BAF (ncBAF) complex; Formation of the polybromo-BAF (pBAF) complex; RMTs methylate histone arginines
Circadian clock: BMAL1:CLOCK,NPAS2 activates circadian expression; Expression of BMAL (ARNTL), CLOCK, and NPAS2; RORA,B,C and NR1D1 (REV-ERBA) regulate gene expression
Metabolism: Activation of gene expression by SREBF (SREBP); PPARA activates gene expression; Regulation of lipid metabolism by PPARalpha
Cellular responses to stimuli: Cytoprotection by HMOX1; Heme signaling
Developmental Biology: Regulation of MITF-M-dependent genes involved in pigmentation; Transcriptional regulation of white adipocyte differentiation
Gene expression (Transcription): RUNX1 interacts with co-factors whose precise effect on RUNX1 targets is not known; Regulation of endogenous retroelements by Piwi-interacting RNAs (piRNAs)
Organelle biogenesis and maintenance: Transcriptional activation of mitochondrial biogenesis
Gene Ontology:
Molecular function: ATP-dependent chromatin remodeler activity; DNA-binding transcription factor binding; nuclear receptor binding; signaling receptor binding; transcription coregulator binding; transcription coactivator activity; transcription coregulator activity; chromatin binding
Biological process: chromatin remodeling; neural retina development; positive regulation of DNA-templated transcription; positive regulation of neuroblast proliferation; positive regulation of cell differentiation; positive regulation of double-strand break repair; positive regulation of myoblast differentiation; positive regulation of T cell differentiation; regulation of G0 to G1 transition; regulation of G1/S transition of mitotic cell cycle; regulation of mitotic metaphase/anaphase transition; regulation of nucleotide-excision repair; regulation of transcription by RNA polymerase II; nucleosome disassembly; positive regulation of G2/M transition of mitotic cell cycle; positive regulation of smooth muscle cell differentiation
Cellular component: chromatin; npBAF complex; nucleoplasm; nucleus; SWI/SNF complex; brahma complex; nBAF complex
Genetic constraint (gnomAD): Loss-of-function variants: 13 observed, 55.6 expected, observed/expected ratio (o/e) 0.23, 90% interval 0.15 to 0.37. The upper end of that interval is the gene's LOEUF score, 0.37, which puts it in group 1 of 6, group 1 being the genes least tolerant of losing a copy. Missense variants: 325 observed, 573.27 expected, observed/expected ratio (o/e) 0.57, 90% interval 0.52 to 0.62. Synonymous variants: 210 observed, 225.57 expected, observed/expected ratio (o/e) 0.93, 90% interval 0.83 to 1.04.
Homologues: Orthologues: chimpanzee SMARCD3 (100% identical), dog SMARCD3 (99% identical), mouse Smarcd3 (99% identical), pig SMARCD3 (99% identical), rat Smarcd3 (99% identical), rabbit SMARCD3 (97% identical), macaque SMARCD3 (95% identical), zebrafish smarcd3b (88% identical), zebrafish smarcd3a (84% identical), guinea pig SMARCD3 (77% identical), Caenorhabditis elegans ham-3 (49% identical), Caenorhabditis elegans swsn-2.2 (45% identical), and 3 more. Paralogues in human: SMARCD1 (73% identical), SMARCD2 (69% identical).
Diseases named in the same sentence as SMARCD3 in open-access papers:
SMARCD3 is named in the same sentence as 58 diseases in open-access papers, as found by Europe PMC text mining. Sharing a sentence is not in itself a finding about the gene and the disease. The quoted sentences say what the papers report.
breast carcinoma (7 papers, 2020 to 2024). "The expression of SMARCD3 was associated with hormone-positive (ER+) breast cancer and correlated with differential long-term disease-free survival." (PMID 39471843, 2024). "These contradictory effects of Smarcd3 in breast cancer suggest a more complex role of this subunit at specific stages of carcinogenesis." (PMID 39471843, 2024). "SMARCD3 was shown to control epithelial–mesenchymal transition in breast cancer cells and epithelial tissue stem cells." (PMID 38862250, 2024). "For example, SMARCD3 transcription is reduced in ER+ breast tumor cells due to methylation of the SMARCD3 promoter, but in ER+ breast cancer, SMARCD3 is still regarded as a tumor suppressor gene." (PMID 38862250, 2024). "SMARCD3 is a very promising gene that has been demonstrated to be a key component in cancers such as breast cancer and medulloblastoma." (PMID 38862250, 2024). "Pathologically, SMARCD3 was reported to regulate epithelial–mesenchymal transition in breast cancer by inducing WNT5A signalling." (PMID 36849558, 2023). "Coincidentally, in SMARCD3-depleted breast cancer cells the proliferation rates were low and the expression of p21 was increased." (PMID 35506290, 2022). "Interestingly, silencing Smarcd3 in EpCAM-breast cancer cells promotes a robust transition from mesenchymal to epithelial phenotype, while its expression in mammary epithelial cells induces EMT." (PMID 39471843, 2024). "SMARCD3 depletion results in lower proliferation rates, increased endoreplication and unresolved DNA damage, suggesting its potential role as a tumour suppressor and a specific prognostic biomarker for breast cancer." (PMID 39471843, 2024). "The levels of SMARCD3, have shown a correlation with breast cancer risks." (PMID 39471843, 2024). "Previous studies have confirmed that SMARCD3 has a cancer-promoting effect in ER+ breast cancer." (PMID 37362244, 2023). "It was reported that knock down SMARCD3 expression could induce mesenchymal-epithelial transition (EMT) of breast cancer cells." (PMID 33125346, 2020). "Previously, it was reported that SMARCD3 could stimulate EMT of breast cancer cells through upregulating WNT5A expression." (PMID 33125346, 2020).
pancreatic cancer (4 papers, 2023 to 2025). "Emerging evidence has implicated SMARCD3 as a critical oncogenic driver in various cancers, including gastric, colorectal, and pancreatic cancers." (PMID 41228321, 2025). "Diverse genetic mouse models of pancreatic cancer and stage-specific Smarcd3 deletion reveal that Smarcd3 loss preferentially impacts established tumors, improving survival especially in context of chemotherapy." (PMID 36653361, 2023). "Recent studies regarding pancreatic cancer have revealed that SMARCD3 amplification in cancer stem cells and its ability to control metabolic and fatty acid pathways are linked to therapeutic resistance." (PMID 41228321, 2025). "A key finding in our work is the discovery that SMARCD3 controls the landscape of lipid metabolism in pancreatic cancer cells." (PMID 36653361, 2023). "Although SWI/SNF subunits often act as tumor suppressors, we show that SMARCD3 is amplified in cancer, enriched in pancreatic cancer stem cells and upregulated in the human disease." (PMID 36653361, 2023). "The regulation of these programs suggests a putative role for SMARCD3 in orchestrating interactions between pancreatic cancer cells and the microenvironment." (PMID 36653361, 2023). "Our work here has led to the identification of SMARCD3 as a potential stem cell-inclusive functional dependency in pancreatic cancer." (PMID 36653361, 2023). "Here we map the epigenetic dependencies of cancer stem cells, cells that preferentially evade therapy and drive progression, and identify SWI/SNF complex member SMARCD3 as a regulator of pancreatic cancer cells." (PMID 36653361, 2023). "Together, these data show that Smarcd3 represent a functional dependency in the context of established and advanced pancreatic tumors." (PMID 36653361, 2023). "Here, the authors suggest SMARCD3 as a potential epigenetic dependency establishing the metabolic landscape in aggressive pancreatic cancer cells and as a potential therapeutic target in pancreatic cancer." (PMID 36653361, 2023). "Using a diverse set of conditional genetic models, we also identified stage-specific roles for Smarcd3 in pancreas cancer." (PMID 36653361, 2023). "Here, we show that SMARCD3 is enriched in the stem cell fraction of pancreatic tumors, and is a potential functional dependency of established cancer cells in vivo." (PMID 36653361, 2023). "SMARCD3 is amplified and enriched in pancreatic cancer stem cells." (PMID 40454484, 2025). "Among genes not previously linked to pancreatic cancer, knockdown or deletion of Smarcd3, an SWI/SNF family member, reduced sphere formation of KPf/fC stem cells by 50%." (PMID 36653361, 2023). "To test whether SMARCD3 is a functional dependency in human pancreatic tumors, we knocked down SMARCD3 in the human FG PDAC cell line." (PMID 36653361, 2023). "BRG1 and SMARCD3, which are shared subunits in cBAF, PBAF, and ncBAF, play oncogenic roles and are important for stemness in pancreatic cancer." (PMID 40454484, 2025). "Further, FOXA1 was co-bound at 75% of common SMARCD3-dependent BAF binding sites; these results support a collaboration between the SMARCD3-containing BAF complex and FOXA1 in pancreatic cancer cells." (PMID 36653361, 2023). "Collectively these data identify SMARCD3 as a SWI/SNF subunit that is required for the growth of aggressive cancer stem cells and that exerts its influence by regulating the metabolic landscape in pancreatic cancer." (PMID 36653361, 2023). "Collectively, these results demonstrate that SMARCD3-BAF, in concert with FOXA1, is an important regulator of fatty acid metabolism, and draws a link between SWI/SNF and stem cell-enriched metabolic programs in pancreatic cancer." (PMID 36653361, 2023).
pancreatic cancer (continued). "Although SMARCD3 expression and function may not be exclusive to cancer stem cells alone, we found that Smarcd3 was a stem-inclusive dependency whose perturbation was sufficient to block the growth of pancreatic cancer stem cells in vivo." (PMID 36653361, 2023).
medulloblastoma (3 papers, 2020 to 2024). A malignant, invasive embryonal neoplasm arising from the cerebellum. "In recent research, high SMARCD3 expression has been shown to be closely related to medulloblastoma metastasis." (PMID 38862250, 2024).
uveal melanoma (3 papers, 2020 to 2023). A melanoma derived from melanocytes of the uveal tract. "The results of the related bioinformatic analysis also suggested that SMARCD3 was a prognostic and potential treatment target maker for colorectal cancer, neuroblastoma, hematologic malignancy, and uveal melanoma." (PMID 37362244, 2023). "Interestingly, it was reported that high expression of SMARCD3 correlates with poorer patient survival in uveal melanoma." (PMID 35323214, 2022). "Therefore, a thorough investigation of SMARCD3 in both cutaneous and uveal melanoma is warranted." (PMID 35323214, 2022).
colorectal cancer (2 papers, 2020 to 2023). A primary or metastatic malignant neoplasm that affects the colon or rectum. "PPI network analysis demonstrated that SMARCD3 could physically interacted with MAPK14 (p38α), MYOD1 and SMAD4 etc., which indicated mechanistic insights underlying SMARCD3 related colorectal cancer metastasis." (PMID 33125346, 2020). "Specifically, colorectal cancer patients with SMARCD3 high expression had poorer OS in comparison with patients with SMARCD3 low expression (Hazard ratio: 2.4, logrank p = 0.00031)." (PMID 33125346, 2020). "Using colorectal cancer data, we showed that SMARCD3 expression was positively correlated with WNT5A, TGF-β and p-MAPK14, which were consistent with previous reports." (PMID 33125346, 2020). "GSEA results showed that SMARCD3 expression was associated with cancer metastasis, TGF-β pathway activation and epithelial-mesenchymal transition (EMT) (p < 0.0001, TCGA colorectal cancer RNAseq data, N = 592)." (PMID 33125346, 2020). "The prognostic value of SMARCD3 was further validated using a larger set of TCGA colorectal cancer RNAseq data." (PMID 33125346, 2020). "Further PPI analysis indicated that SMARCD3 might promote colorectal cancer metastasis through MAPK14, MYOD1 or SMAD4 related pathways." (PMID 33125346, 2020). "Hence, screening for drugs or chemicals targeting SMARCD3 may exert important clinical impact on colorectal cancer management." (PMID 33125346, 2020). "Using TCGA colorectal cancer RNAseq and protein expression data, we demonstrated that WNT5A and TGFB1 were positively correlated with SMARCD3; WNT5A and TGFB1 were overexpressed in SMARCD3 high group." (PMID 33125346, 2020).
gastric cancer (2 papers, 2024 to 2025). A primary or metastatic malignant neoplasm involving the stomach. "Given its central role in coordinating key oncogenic pathways and Epithelial–Mesenchymal Transition (EMT), a deeper understanding of SMARCD3’s function in gastric cancer signaling is therefore critical for identifying novel therapeutic targets." (PMID 41228321, 2025). "SMARCD3 acts as a critical epigenetic regulator that promotes EMT in gastric cancer patients through the integration of PI3K-AKT and WNT/β-catenin signaling." (PMID 41228321, 2025). "Targeting this SMARCD3-mediated mechanism offers a promising therapeutic strategy to inhibit metastasis and improve outcomes for patients with gastric cancer." (PMID 41228321, 2025). "Our findings establish SMARCD3 as a pivotal epigenetic regulator that drives an aggressive gastric cancer phenotype through the orchestration of epithelial–mesenchymal transition (EMT)." (PMID 41228321, 2025). "Kaplan-Meier survival analysis indicated that higher SMARCD3 expression correlates with poorer overall survival in gastric cancer patients (HR 2.16, p < 0.001)." (PMID 38927986, 2024). "This study investigates the role of SMARCD3 in gastric cancer by comparing its expression in signet ring cell (SRC) and well-differentiated (WD) groups within gastric cancer cell lines and tissues." (PMID 38927986, 2024). "Next-generation sequencing (NGS) was performed after the SMARCD3 gene was overexpressed in the MKN45 and MKN74 gastric cancer cell lines." (PMID 41228321, 2025). "Taken together, these findings support a regulatory role for SMARCD3 in modulating EMT through the PI3K-AKT and WNT/β-catenin signaling pathways in gastric cancer cells." (PMID 41228321, 2025). "Despite its known oncogenic role, the precise molecular mechanism by which SMARCD3 epigenetically integrates the PI3K-AKT and WNT/beta-catenin pathways to drive EMT in gastric cancer remains undefined." (PMID 41228321, 2025). "The aim of this study is to elucidate the molecular mechanism through which SMARCD3 integrates with the PI3K-AKT and WNT/β-catenin signaling pathways to promote EMT and gastric cancer progression." (PMID 41228321, 2025). "Collectively, these findings indicate that SMARCD3 overexpression promotes the nuclear accumulation of Snail via the PI3K/Akt signaling axis, thus facilitating EMT and contributing to gastric cancer progression and poor prognosis." (PMID 41228321, 2025). "This study demonstrates that SMARCD3 overexpression in gastric cancer (GC) serves as a negative prognostic biomarker, correlating with significantly poorer overall survival." (PMID 41228321, 2025). "Compelling evidence from our group indicates that high SMARCD3 expression serves as a robust negative prognostic factor for gastric cancer patients, correlating with markedly reduced survival rates." (PMID 41228321, 2025). "The study concludes that SMARCD3 overexpression may serve as a negative prognostic marker and a potential therapeutic target in gastric cancer treatment due to its role in promoting EMT." (PMID 38927986, 2024).
glioblastoma (2 papers, 2023 to 2024). The most malignant astrocytic tumor (WHO grade IV). "Furthermore, SMARCD3 was most highly expressed in brain lower grade glioma (LGG) and glioblastoma multiforme (GBM), although its expression in both healthy and tumorous tissues was similar." (PMID 38862250, 2024). "Pan-cancer analyses using The Cancer Genome Atlas datasets revealed that the levels of SMARCD3 and DAB1 mRNA expression were not correlated (R = 0.17, P < 2.2 × 10–16), including no positive correlation in low-grade glioma and glioblastoma (R = −0.11, P = 0.0023)." (PMID 36849558, 2023).
lung adenocarcinoma (2 papers, 2020 to 2021). A carcinoma that arises from the lung and is characterized by the presence of malignant glandular epithelial cells. "For this, we made use of a GR activity score (explained above) and the lung adenocarcinoma dataset from TCGA (91/877 tumours harboured SWI/SNF mutations; SMARCB1 18.09%; SMARCC2 9.52%, SMARCD2 6.66%, SMARCD3 1.90%, ARID1A 29.52%, ARID2 31.42%, SMARCE1 2.85%)." (PMID 34272384, 2021).
pancreatic ductal adenocarcinoma (2 papers, 2023 to 2024). An infiltrating adenocarcinoma that arises from the epithelial cells of the pancreas. "In pancreatic ductal adenocarcinoma, SMARCD3 is considered an epigenetic regulator and a potential therapeutic target." (PMID 38862250, 2024).
viral infections (2 papers, 2022 to 2025). "In infectious diseases, including viral infections like influenza and Coronavirus Disease 2019(COVID-19), SMARCD3 is involved in regulating the immune response." (PMID 41221285, 2025). "The 8-gene signature included three genes over-expressed in bacterial infections (SMARCD3, ICAM1, EBI3; “bacterial genes”) and five over-expressed in viral infections (JUP, SUCLG2, IFI27, FCER1A, HESX1; “viral genes”)." (PMID 36543117, 2022).
bladder cancer (1 paper, 2024). "As a result, we performed an immunotherapy and discovered that in the renal cell carcinoma (GSE67501) and bladder cancer (IMvigor210) datasets, there were notable changes in the immune response effects among the SMARCD3 low and high-expression groups." (PMID 38862250, 2024).